GCG (glucagon)
Diseases named in the same sentence as GCG in open-access papers (continued):
Sharing a sentence is not in itself a finding about the gene and the disease.
steatosis (25 papers, 2013 to 2026). Increased lipid within the cytoplasm of cells. "Still, we cannot exclude that increased hepatic PDE4D expression and impaired glucagon‐cAMP signalling contribute to hepatic steatosis in Atp8b1 mutant mice." (PMID 40851490, 2025). "In turn, glucagon resistance leads to progression of steatosis through blocking glucagon induced hepatic β-oxidation and lipolysis." (PMID 40069760, 2025). "Another reason for steatosis is the existence of glucagon resistance because it can increase liver fat33–35." (PMID 38816541, 2024). "It now appears that the high fasting levels of glucagon in patients with T2DM are more related the occurrence of NAFL and steatosis of the liver, which causes resistance to the actions of glucagon with resulting hyperaminoacidemia." (PMID 35990325, 2022). "Concerning SGLT-2 inhibitors’ role on the glucagon-to-insulin ratio, they are able to improve it, therefore increasing ketogenesis in the liver and leading to protection against steatosis." (PMID 33921359, 2021). "Furthermore, steatosis-induced hepatic glucagon resistance increases circulating amino acids which in turn induces further hyperglucagonemia." (PMID 40069760, 2025). "Here, steatosis might—through hepatic glucagon resistance along with impaired hepatocyte function—lead to the disruption of the liver alpha cell axis, a direct feedback mechanism between hepatic amino acid metabolism and pancreatic glucagon secretion." (PMID 37078380, 2023). "Participants receiving tocilizumab increased visceral adipose tissue mass and showed similar trends for whole body fat mass; therefore on a very speculative note, the augmented glucagon secretion could be secondary to steatosis." (PMID 31636570, 2019). "Induced steatosis was reversible after withdrawal of lipogenic substrates and a further reduction in cellular fat content was observed following treatment with different antisteatotic compounds, such as metformin, glucagon, olaparib and antioxidants." (PMID 30250238, 2018). "However, in the present study, the continuous association between liver fat content and the glucagon–alanine index points to an effective adaption of the liver–alpha cell axis to hepatic glucagon resistance in individuals without clinical steatosis." (PMID 33275161, 2021). "In addition, we showed an increased level of serum glucagon, which may further facilitate steatosis due to glucagon suppression of VLDL secretion." (PMID 24244493, 2013). "In methionine/choline-deficient diet-fed mice, two-week treatment with a dual GLP-1/glucagon co-agonist (G49) ameliorated NASH by reducing inflammation, steatosis, oxidative stress, and apoptosis and increased mitochondrial biogenesis." (PMID 32823659, 2020). "Dose response data shows that maximal effects of glucagon and TNF alpha for reduction or reversal of insulin-induced steatosis are active at >1 μg/ml glucagon and 100 nM TNF alpha, respectively." (PMID 29430572, 2017). "This was improved to some extent in islets from the STZ/HFD-32 fed mice treated with R-Tf-D-LP4 at the steatosis stage, but was completely restored in R-Tf-D-LP4 peptide-treated animals at the NASH stage, where the glucagon stained α-cells were localized as expected around the edge of the islet." (PMID 32093016, 2020). "However, in the STZ/HFD-32 fed mice with steatosis or NASH, the islets demonstrated an impaired morphology in which the glucagon-producing cells infiltrated into the islets." (PMID 32093016, 2020).
myocardial infarction (24 papers, 2010 to 2025). Gross necrosis of the myocardium, as a result of interruption of the blood supply to the area, as in coronary thrombosis. "After acute myocardial infarction, the sympathetic nervoussystem activation increases the levels of glucagon, growth hormones,glucocorticoids, and catecholamines." (PMID 39867189, 2025). "Antagonizing glucagon action represents a novel and effective pharmacological intervention to alleviate cardiac dysfunction and adverse remodelling post-myocardial infarction." (PMID 30626440, 2019). "Although cardiac contractility can be enhanced by glucagon administration, it will increase cardiac mortality since glucagon increases cardiomyocyte consumption of energy after myocardial infarction." (PMID 29576852, 2018). "Some have reported that glucagon might be antiarrhythmic in myocardial infarction, at least in dogs." (PMID 37629010, 2023). "In a mouse model of myocardial infarction, an antibody against glucagon improved cardiac function, and one might speculate that such an approach might be feasible in humans." (PMID 37629010, 2023). "Under extreme stress conditions, such as after acute myocardial infarction (AMI) and cardiac arrest, epinephrine levels can markedly increase and may have a greater effect on glucagon secretion in the critically ill patient." (PMID 33466656, 2021).
pancreatic neuroendocrine tumor (24 papers, 2009 to 2026). Pancreatic endocrine tumor, also known as pancreatic neuroendocrine tumor (PNET), describes a group of endocrine tumors originating in the pancreas that are usually indolent and benign, but may have the potential to be malignant. "Mahvash disease is a rare autosomal recessive condition caused by biallelic inactivating variants in the GCGR gene, impairing glucagon signaling and leading to alpha-cell hyperplasia and pancreatic neuroendocrine tumors (PNETs)." (PMID 41649336, 2026). "Direct inhibition of glucagon signaling, however, raises safety concerns as it causes α cell hyperplasia, a possible precursor lesion of pancreatic neuroendocrine tumors (PNETs)." (PMID 21853126, 2011). "Six cases of clinically functional glucagon-producing neuroendocrine tumors of the pancreas were identified (for an estimated prevalence of glucagonomas among all resected functioning and non-functioning PanNETs in the institutions: 0.5%)." (PMID 39331358, 2024). "Glucagonoma (GCGN) is a rare pancreatic neuroendocrine tumor (pancreatic neuroendocrine tumor, pNET) originating from pancreatic islet A2 cells, whereby the islet cells secrete abundant glucagon." (PMID 39252948, 2024). "A biopsy of the pancreatic tumor revealed a pancreatic neuroendocrine tumor, and immunoperoxidase staining revealed glucagon-positive cells." (PMID 29069049, 2017). "VHL-associated pancreatic neuroendocrine tumors (PNET) afflict 12–17% of VHL patients, and these tumors have been demonstrated to exhibit focal positivity for glucagon." (PMID 19340311, 2009). "In light of the clinical, laboratory, and imaging findings, the leading diagnosis was a pancreatic neuroendocrine tumor that had initially appeared non‐functional but subsequently demonstrated glucagon hypersecretion, clinically manifesting as necrolytic migratory erythema." (PMID 41403981, 2025). "The second major class of pancreatic cancer is pancreatic neuroendocrine tumors (also termed islet cell tumors), which arise from cells that make up the endocrine gland of the pancreas, which secretes insulin, gastrin, and glucagon into the serum to regulate glucose uptake and metabolism." (PMID 37371782, 2023). "Hyperplasia of α-cells under defective glucagon signaling is not unique to rodent models, and a human case carrying a homozygous glucagon receptor mutation has been reported to show α-cell hyperplasia and islet cell tumor." (PMID 23671715, 2013). "Glucagonoma, a slow-growing pancreatic neuroendocrine tumor, autonomously secretes excessive amounts of glucagon due to the lack of regulation by the body’s negative feedback mechanisms, leading to glucagonoma syndrome." (PMID 41150819, 2025).
atherosclerosis (23 papers, 2013 to 2025). A disease characterized by the build-up of fatty material and calcium deposition in the arterial wall resulting in partial or complete occlusion of the arterial lumen. "KEGG pathway analysis suggested that the metabolism of xenobiotics by cytochrome P450 was the most enriched pathway, followed by complement and coagulation cascades, glucagon signaling pathway, lipid and atherosclerosis, and PI3K-Akt signaling pathway (SFigure 1B)." (PMID 34423049, 2021).
liver disease (22 papers, 2010 to 2026). "Our findings demonstrate that itaconate has a glucagon-potentiating effects in the liver, suggesting that itaconate may play a significant role in the pathogenesis of metabolic-associated liver diseases." (PMID 40323920, 2025). "We have previously reported hepatic glucagon resistance in individuals with T2D and steatotic liver disease." (PMID 40271226, 2025). "Plasma glucagon levels are increased in cirrhotic patients and experimental models of portal hypertension, due to decreased hepatic clearance of glucagon as well as an increased secretion of glucagon by pancreatic α cells." (PMID 22666604, 2012). "Finally, we summarize and discuss the potential impact of glucagon on the treatment of liver diseases." (PMID 30995792, 2019). "The role of glucagon in the splanchnic hyperemia of portal hypertension provides a rationale for the use of somatostatin and its synthetic analogs to reduce glucagon level, thereby treating portal hypertension." (PMID 22666604, 2012). "Controls and T2D without the liver disease had similar fasting glucagon levels." (PMID 36686477, 2022). "Additionally, in the pathological state of the liver, glucagon-induced acetylation of energy-sensing factors such as signal transducer and activator of transcription–3 (STAT3) provide a potential treatment strategy for liver disease." (PMID 30995792, 2019). "Fasting glucagon levels were lower but similar in patients with T2DM and without liver disease and in controls." (PMID 37189715, 2023).
pancreatic cancer (22 papers, 2012 to 2025). "Within the NETs, glucagon-producing tumours of the pancreas are fairly rare and can be associated with syndromes such as MEN1." (PMID 25520848, 2014). "Importantly, Kaplan–Meier survival analysis revealed a significant association between higher GCG expression and improved overall survival (HR = 0.82, logrank p = 0.016), emphasizing its potential role as a prognostic marker in pancreatic cancer." (PMID 39777709, 2025). "Dipeptidyl peptide 4 (DDP-4) inhibitors or gliptins (sitagliptin, saxagliptin, and linagliptin) inhibit glucagon release resulting in reduced blood glucose levels, however significant side effects include increased risk of heart failure, pancreatitis and pancreatic cancer." (PMID 28862678, 2017). "In most other tissues, GCG expression remained low and consistent between normal and tumor samples, further underscoring the specificity of GCG overexpression in pancreatic cancer." (PMID 39777709, 2025). "In contrast, pancreatic tumors originating from endocrine cells are uncommon, and typically exhibit excessive hormone secretion, most commonly insulin or glucagon." (PMID 39200178, 2024). "We analyzed the infiltration of pancreatic cancer cells into pancreatic islets via double-immunolabeling of human pancreatic cancer tissues with insulin or glucagon and the pancreatic cancer cell marker cytokeratin 19 (CK-19) or Mucin-1 (MUC1)." (PMID 33440856, 2021). "Glucagonoma diagnosis involves typical clinical symptoms, elevated serum glucagon level, and the presence of a pancreatic tumor." (PMID 30631852, 2018). "Glucagonoma can be definitively diagnosed by the presence of pancreatic tumor, typical symptoms, and elevated glucagon levels." (PMID 30631852, 2018). "Pancreatic tumors strongly produced and secreted glucagon, suggesting that they derived from glucagon- and GFAP-positive islet cells." (PMID 27769070, 2016). "Because mouse ApcMin/+ colon, LLC lung, and human pancreatic tumors were found to produce large amounts of VEGF/PDGF62–69, we wonder whether tumors promote neural-associated glucagon secretion via VEGFR/PDGFR signaling in a manner similar to fly Pvr signaling." (PMID 39924534, 2025). "Similarly, GCG expression was markedly higher in pancreatic tumor tissues, with the median value reaching approximately 35,000, compared to nearly zero in normal pancreatic tissues." (PMID 39777709, 2025). "The results showed a clear positive signal in pancreatic islets, but, interestingly, glucagon levels significantly decreased in pancreatic tumor tissues, indicating that decreased glucagon levels might be a general phenomenon in tumor tissues." (PMID 38072640, 2024). "However, the diagnosis of GS still requires an elevated serum glucagon level (usually 500–1000 pg/mL) and imaging confirming a pancreatic tumor." (PMID 29069049, 2017). "To confirm glucagon expression in CRC samples, we stained pancreatic islets from patients with pancreatic cancer as a positive control to test if the staining worked correctly." (PMID 38072640, 2024). "Histopathology of the pancreatic tumour revealed a glucagonoma with positive immunostaining for glucagon, chromogranin A and synaptophysin; negative immunostaining for gastrin, insulin, serotonin, somatostatin and pancreatic polypeptide." (PMID 25520848, 2014). "GCG expression did not significantly influence survival outcomes in bladder cancer, esophageal squamous cell carcinoma, renal papillary cell carcinoma, lung adenocarcinoma, and pancreatic cancer." (PMID 39777709, 2025). "Interestingly, as compared to those with pancreatic benign diseases (n = 15), patients bearing pancreatic cancer without (n = 18) or with weight decline (> 1.5% per month) (n = 21) within three months prior to surgery potently exhibited higher serum glucagon concentration." (PMID 39924534, 2025).
colitis (21 papers, 2010 to 2025). Inflammation of the colon. "A positive correlation occurred between GCG and GPBAR1 in human samples and animal models of colitis." (PMID 35406751, 2022).
Cognitive impairment (20 papers, 2013 to 2026). Abnormal cognition is characterized by deficits in thinking, reasoning, or remembering. "Glucagon suppresses hepatic mTORC activation, and 1 potential mechanism by which impaired glucagon signaling could contribute to cognitive impairment is through brain glucagon resistance, leading to increased mTORC activity." (PMID 40271226, 2025).
depression (20 papers, 2017 to 2026). "A genome-wide study of suicidal behaviors in depression found that the Glucagon signaling pathway was most abundant in major depression disorder." (PMID 35770096, 2022). "In contrast, another study reported a significant positive relationship between SH (requiring assistance from others and unconsciousness or application of glucagon) in the past year and a DSM-IV depression diagnosis." (PMID 34855927, 2021). "Several studies have proposed that anxiety and depression may activate the sympathetic adrenal medulla system, stimulate adrenocorticotropic hormone (ACTH) secretion, and elevate levels of glucocorticoids, glucagon, and catecholamines." (PMID 40870492, 2025).
malnutrition (20 papers, 2018 to 2026). Inadequate nutrition resulting from poor diet, malabsorption, or abnormal nutrient distribution. "This multifactorial malnutrition model proposes that glucagon-induced nutrient deficiencies destabilize epidermal integrity, predisposing to cellular breakdown, inflammation and impaired wound healing." (PMID 40300042, 2025). "These mediators not only mediate lymphocyte apoptosis but also stimulate the secretion of catabolic hormones such as glucagon, cortisol, and catecholamines, thereby exacerbating malnutrition." (PMID 41393928, 2025). "In link, glucagon induction of inflammatory mediators, such as arachidonic acid derivatives, contributes to generalized malabsorption and malnutrition." (PMID 35498123, 2022). "There is other evidence that changes of blood glucose levels during malnutrition occur due to an increased glucose production from other pathways, reducing insulin synthesis, stimulating the production of glucagon, and increasing circulating epinephrine levels." (PMID 32455002, 2020). "Concomitant malnutrition in T2DM patients has been reported to elevate levels of HbA1c, RBG, insulin, and glucagon." (PMID 40977986, 2025). "Malnutrition and lack of physical activity led to tuberculosis patients stimulating adrenaline, glucagon, and cortisol at the same time, thereby increasing glucose levels." (PMID 32596376, 2020).
pancreatitis (20 papers, 2010 to 2026). Inflammation of the pancreas. "Likewise, the pancreas is a vital metabolic organ responsible for maintaining glucose homeostasis through the secretion of insulin, glucagon and a variety of digestive enzymes; heightened SUV levels in the pancreas are linked to pancreatitis." (PMID 39189415, 2024). "Given that GLP-1 and GLP-2 are structurally related by a common precursor protein, proglucagon, it is possible that the increased pancreatitis risk associated with GLP-1 and GLP-2 agonists may be mediated by similar biological mechanisms." (PMID 39350843, 2024). "A large prospective double-blinded randomization study showed that a combination of glucagon and nitroglycerin prevents post-ERCP complications such as pancreatitis and cholangitis." (PMID 39001295, 2024).